CD4 (CD4 molecule)
Diseases named in the same sentence as CD4 in open-access papers (continued):
Sharing a sentence is not in itself a finding about the gene and the disease.
tumor (continued). "In this analysis, we additionally found that immune cells (CD4, CD8, and CD68) had an increased distance to tumor cells in HIV-associated tumors, using Euclidean distance as well as neighborhood enrichment analysis in order to assess the spatial relationships between different cell types." (PMID 40459946, 2025). "However, our recent study demonstrated that CAFs derived from tumor tissues promoted immune evasion by suppressing the function of CD4+ and CD8+ T cells." (PMID 40940956, 2025). "CD4+ Treg cells in the tumor microenvironment (TME) express high levels of PD-1 (programmed cell death protein 1), suggesting that PD-1 blockade might enhance Treg’s immunosuppressive function." (PMID 40552264, 2025). "Consistent with our previous publication demonstrating the role of MDSCs in Treg cell expansion in tumor-bearing mice, we observed that Treg cells and the CD4 population were significantly reduced in CMTM4 KD tumors when compared to mice bearing control wild-type tumors." (PMID 39948411, 2025). "Also of interest is patient 101.02, where a high number of tumor digest-reactive CD4+ T cells were observed." (PMID 40107242, 2025). "Therefore, CD4+ T cells are important for the remodeling of tumor blood vessels and the increase of TA-HEVs, and they also control the recruitment and functional phenotype of CD8+ T cells during anti-CTLA-4 therapy." (PMID 40460830, 2025). "CXCR5+ CD8+ T cells, like their CD4+ counterparts, also express high levels of PD-1, and may exhibit an “exhausted” phenotype in the tumor microenvironment, making them potential targets for ICIs." (PMID 40552264, 2025). "The tumor necrosis caused by TACE increased the release of tumor-associated antigens, which has been proven to recruit DCs and increase AFP-specific CD4+T-cell response, thus synergizing with ICIs to increase cytotoxic T lymphocytes and decrease tumor-infiltrating Treg cells." (PMID 40129919, 2025). "The functions of Th1 and Th2 populations are distinctly different, with Th1 cells boosting anti-tumor immunity and Th2 cells aiding in tumor immune evasion, although both cell types originate from CD4+ T cells and inhibit each other to maintain immune system balance." (PMID 40243892, 2025). "Interestingly, in the presence of the OVA-expressing tumor, also the CD4 signal was detected and superior in the oligoDOMTM-treated group, unlike what was observed with the naïve mice." (PMID 40160825, 2025). "Results demonstrated that DIFP-FA + US not only effectively eradicated PDX tumor tissue but also stimulated and enhanced APCs function by releasing DAMPs, leading to the recruitment and infiltration of CD4+ T helper cells and CD8+ cytotoxic T cells into the tumor tissue." (PMID 40104638, 2025). "Moreover, SPOP was positively correlated with CD8+ T cells, CD4+ T cells, B cells, and macrophages and correlated with effector genes of tumor‐infiltrating immune cells." (PMID 39499771, 2025). "Further relevance analysis between genes and immunization revealed a decreased proportion of memory CD4+ T cells in the tumor group, with RFWD3 positively correlating with M1 macrophages, ZNF626 positively correlating with M2 macrophages, and SLK negatively correlating with M1 macrophages." (PMID 40002911, 2025). "Interestingly, depleting CD4+ T cells enhanced the anti-tumor efficacy of FL/GM-DCs, possibly due to the reduction in Tregs, thereby decreasing immunosuppression and potentiating the therapeutic effect against cancer." (PMID 40977690, 2025). "In addition, AUROC of more than 50% subpopulations of CD3+CD4+PD-1+ or more than 80% subgroups of CD3+CD8+PD-1+T cells was greater than that of residual tumor size (AUROC = 0.58)." (PMID 41011166, 2025). "Last, we aimed to determine the extent to which the differential distribution patterns of tumor-infiltrating CD4+ cells could serve as predictors of therapy efficacy in a clinical setting." (PMID 40561008, 2025).
tumor (continued). "Flow cytometry analysis revealed an increase in the proliferative (Ki67+), activated (CD69+), and cytotoxic (TNFα+, IFNγ+, GzmB+) CD8+ and CD4+ T cells in tumor tissues and spleens of GL261 tumor-bearing mice treated with cinobufagin, compared to the vehicle-treated group." (PMID 39901195, 2025). "This suggests YY1 may contribute to an immunosuppressive tumor microenvironment as seen in breast cancer models where naive CD4 + T cells were found to convert to regulatory T cells supporting immunosuppression." (PMID 41327312, 2025). "The findings revealed that the overexpression of FLT3LG in tumor cells effectively impeded tumor growth, augmented the proliferation of CD4+ and CD8+ T cells, suppressed the activity of Treg cells, and significantly potentiated the efficacy of anti-PD-1 therapy." (PMID 40329265, 2025). "The resulting reduction in intra-tumoral granulocytic-MDSCs (G-MDSCs) and Treg could contribute to the observed increase in tumor-infiltrating CD4+ T cells." (PMID 41246345, 2025). "Additionally, intrapleural CAR-T-cell administration promoted the elimination of extrathoracic tumour sites as a result of early CD4(+) T-cell activation and T-cell-mediated cytotoxicity." (PMID 40906384, 2025). "Furthermore, in patients undergoing adoptive transfer of TILs, tumor regression mediated by both CD4+ and CD8+ T cells is specifically directed against neoantigens, underscoring the critical role of neoantigen recognition in effective antitumor responses." (PMID 41584608, 2025). "Interestingly, galunisertib increased the recruitment of CD4 T cells, but they remained excluded in the outer ring of the tumours, while setanaxib treatment increased the intratumoural presence of CD4 T cells." (PMID 40820091, 2025). "Within the TC-TLS, there was a greater abundance of various T cell subsets, including CD8+PD-1+, CD8+PD-1+TIM-3−, CD8+LAG-3−PD-1+TIM-3−, CD8+TIM-3-, CD8+LAG-3−TIM-3−, CD4+FoxP3−, CD4+CTLA-4−, and CD4+PD-L1+ T cells, compared with that in the tumour and stromal regions." (PMID 39901202, 2025). "This example demonstrates how the specific cytokine environment within the tumor can influence the effectiveness of immune checkpoint therapy by directing CD4+ T cells away from a Th1 phenotype towards Th17 cells, which may compromise anti-cancer immunity." (PMID 39325360, 2025). "Tumor cell-based therapies can stimulate the immune system by presenting tumor antigens, which may activate CD4 T cells and microglia, leading to enhanced anti-tumor activity." (PMID 41374974, 2025). "Our further analysis has pointed to the enrichment of MHCII-associated antigen-processing and presentation pathway post-therapy and in the longest survivor, which led us to hypothesize that anti-tumor CD4+ T cells are involved in response to oHSV therapy." (PMID 39885128, 2025). "Expanded CD4 T-cells, which may have been amplified due to infection or as a response to the tumor, were investigated by focusing on the 16 unique DEGS of the CD4_EM cells." (PMID 39857770, 2025). "The DC3 subset may be crucial for tumor immunity and is capable of inducing autologous naïve CD4+ helper T cell responses and IL-17 production, as well as activating CD8+ T cells, with lower efficiency than cDC2s." (PMID 41430039, 2025). "In addition, HVEM expression was found to result in fewer tumor-infiltrating CD4+, CD8+, and CD45RO+ lymphocytes." (PMID 40243455, 2025). "Blocking IL-27 (using antibodies against its p28 subunit) reduced the number of CD4+ T-lymphocytes in the tumor microenvironment (TME), likely due to decreased expression of C-X-C chemokine receptor 3 (CXCR3) on CD4+ T-cells, a receptor responsible for their migration to tumors." (PMID 40725022, 2025). "In sharp contrast, in ICI-treated mice 64Cu-CD4-Nb1 mainly accumulated within the tumor cores." (PMID 40561008, 2025).
tumor (continued). "Studies have shown that the IL-4 signaling may promote tumor immune escape by activating CD4+ regulatory T cells (Tregs) and inhibiting the function of NK cells." (PMID 40656893, 2025). "Importantly, considering anti-tumor T cells as a class, the CD4 subset often facilitates CD8+ responses, but similar challenges exist for such cells when functioning as effectors in the dynamic cancer TME." (PMID 41479781, 2025). "This is an important question, as circulating, blood cytotoxic CD4+ T cells that communicate with the tumor would share antigenic specificity with their tumor-resident counterparts, making them an accessible means to monitor intratumoral immunity or to develop ex vivo cellular therapies." (PMID 40299576, 2025). "However, combination therapy with PD-1/PD-L1 inhibitor 2 and TOE significantly increased the proportion of CD8+ T cells in the tumor microenvironment, while the proportion of CD4+ T cells remained unchanged." (PMID 40109332, 2025). "Notably, CD4+ T cells appear particularly essential for the anti-tumor effects observed following B7-H3 inhibition in mouse models." (PMID 40801642, 2025). "The CD4/CD8 imbalance indicates a disrupted immunoregulatory balance, which is a hallmark of many pathological states and is effectively exploited here to facilitate tumor engraftment." (PMID 41463273, 2025). "Notably, CD8+ infiltration in tumor cores and CD4+ presence in peripheral and stromal zones were independently linked to reduced OS." (PMID 41020848, 2025). "In human and mouse tumor tissues, regulatory T cells correlated with CD4+ cell densities." (PMID 40561008, 2025). "Notably, 94.3% of malignant CD4+ T cells in tumor stage MF lesions exhibited complete CD5 loss compared to only 76.6% in patch-plaque MF lesions, suggesting antigen escape in tumor stage disease." (PMID 41226451, 2025). "We further show how the presence of HER2+ tumour cells results in a suppressive phenotype for CD4+ cells, and that depletion of CD4+ cells leads to the elimination of influenza virus infection-expanded DCCs, dependent on CD8+ cells with restored effector activity." (PMID 40739350, 2025). "However, the ratio of CD4+ to CD8+ positive T cells in non‐stressed tumour‐developed (CANTumor) mice was significantly higher compared to all other groups (one‐way ANOVA, *p < 0.05)." (PMID 40172096, 2025). "Intriguingly, deletion of CD8+ T cells significantly repaired the tumor growth restriction caused by VSIG4-KO, while deletion of CD4+ T cells did not affect tumor growth in the VSIG4-KO group." (PMID 39920772, 2025). "The effect of CD4+ T cells on tumor cells varies greatly depending on the subset." (PMID 40257446, 2025). "Although cytotoxic CD8+ T lymphocytes are essential for tumor cell elimination, they may suppress CD4+ T cell functions and often lack robust effector-memory capabilities." (PMID 41268299, 2025). "Within the immune cell islands, Cd4+ and Cd8+ T cells increase in frequency in the HMGA1-deficient crypt cells, the latter of which could reflect an increase in tumor-infiltrating T lymphocytes." (PMID 39895630, 2025). "By day 21, the OVV-01 group exhibited markedly higher levels of hCD3+ T cells, hCD3+CD8+ T cells, and hCD3+CD4+ T cells in both peripheral blood and tumor compared to the control and OVV-00 groups, indicating that OVV-01 has a stronger immunostimulatory effect than OVV-00." (PMID 40873562, 2025). "The impaired DCs fail to properly activate CD8+ and CD4+ T-cells, which results in decreased T-cell infiltration, reduced cytolytic activity, and compromised neoantigen recognition, ultimately potentiating tumor immune evasion." (PMID 41007774, 2025). "Moreover, tumor-infiltrating MAIT cells in CRC are CD4+ and Foxp3+ and express high levels of CD39, which is an exhaustion indicator." (PMID 40422223, 2025).
tumor (continued). "Second, analysis of tumor-infiltrating immune cells 7 days after treatment showed that both CD4 and CD8 T-cell fractions were elevated following RMC-7977 + palbociclib treatment, with a notably higher fraction of CD4 T cells in tumors treated with the triple combination." (PMID 40299790, 2025). "ADAR1 (RNA‐editing enzyme can lead to the creation of missense mutations in coding sequences) is highly expressed in lung cancer tissues, which also increases the expression of tumor cells such as M0 and M2 macrophages, but decreases the levels of CD4+ T cells in the effector immune cells." (PMID 39927632, 2025). "Deactivating MYC in existing adenocarcinomas immediately reverses stromal changes and causes tumor regression, which is not dependent on CD4+CD8+ T cells but heavily relies on the return of NK cells." (PMID 40732268, 2025). "Notably, the correlation between PTPN21 and multiple immune cell markers, such as CD4 + T cells and macrophages, hints at its potential role in regulating the tumor immune microenvironment, paving the way for the development of novel therapeutic strategies." (PMID 40305474, 2025). "The enhancement of activated CD4+ memory T cells may stem from previous immunological responses to tumor antigens, with their activated condition potentially supporting anti-tumor immunity." (PMID 40842994, 2025). "To determine which types of immune cells are activated by B002T‐LP004 during tumor rejection and, thus, which types of immune cells play a more important role in tumor rejection, we first cleared CD4+ T, CD8+ T, and NK cells and macrophages from C57BL/6jGpt mice bearing Mc38‐hHER2 individually." (PMID 40606778, 2025). "Notably, Th2 cells are involved in mediating cancer immunity, and blocking TGF-β signaling in CD4+ T cells has been shown to remodel the tumor microenvironment, potentially curbing cancer progression." (PMID 40004479, 2025). "However importantly, M002-treated CD4+ T cells influenced other immune cells in the tumor and periphery similar to saline-treated CD4+ T cells, which cannot account for the beneficial effects imparted by M002-treated CD4+ T cells." (PMID 39885128, 2025). "Tumor-specific CD4+ T cell responses have traditionally been studied in the ‘post-hoc’ setting following their generation by targeted vaccination, immune checkpoint blockade, or at late stages of tumor outgrowth." (PMID 40196575, 2025). "Accordingly, enhancing the efficacy of immune surveillance by activated CD4 memory T cells may represent a pivotal strategy for counteracting tumor immune evasion." (PMID 40352921, 2025). "As expected from the relatively low response rates in patients with NSCLC, CD4+ T cells were significantly enriched in the tumor margin, whereas only a few patients presented increased CD4+ T cell accumulation within the tumor core between baseline and after αPD-L1 treatment." (PMID 40561008, 2025). "By applying TCRseq together with scRNAseq on CT26 MMRd tumor infiltrating cells, we observed expansion of multiple clones of CD4+ and CD8+ T cells following treatment with the combination of PD-1 blockade and vaccination compared to untreated or anti-PD-1 treated tumors." (PMID 41256707, 2025). "Estrogen promotes cell proliferation and inhibits apoptosis by upregulating ZNF626 and SLK genes and downregulating the RFWD3 gene, while also leading to a decline in memory CD4+ T cells and a shift in macrophage phenotypes from M1 to M2 within the tumor inflammatory microenvironment." (PMID 40002911, 2025). "Moreover, the proportion of NKG2A+ cells was significantly higher in tumor infiltrating CD8+ T cells also expressing CD69+ or GZB+ as well as in CD69+ CD4+ Tconv cells." (PMID 39706891, 2025). "Extracellular ATP activates the P2X7 receptor on Mφ surface, inducing NLRP3 inflammasome-dependent IL - 1β release and upregulating the expression of MHC-II molecules and costimulatory molecules CD80/CD86, thereby promoting the cross-presentation of tumor antigens to CD4+ T cells." (PMID 41019083, 2025).
tumor (continued). "In contrast, the proportion of CD4+ T cells was significantly elevated in tumor tissues." (PMID 41061966, 2025). "CD4+ infiltration was 284.82% higher in the anti-PD1 + RT tumor than in anti-PD1 alone (p = 0.042)." (PMID 41514652, 2025). "By internalizing tumor-associated antigens (TAAs) and processing them through MHC-II pathways, B cells present immunogenic peptides to CD4+ T cells via TCR engagement, crucially licensing dendritic cells for subsequent CD8+ T cell priming through CD40-CD40L costimulatory interactions." (PMID 41246318, 2025). "Additionally, the risk score was significantly positively correlated with several tumor‐immune‐related cell types, including M1 macrophages, M2 macrophages, CD4+ T cells, neutrophils and myeloid dendritic cells." (PMID 40561176, 2025). "Interestingly, beyond their immunomodulatory capacity through secretion of soluble factors, CD4+ T cells were also shown to influence anti‐tumour immune responses by exhibiting effector cytotoxic activity." (PMID 40878038, 2025). "Moreover, interactions between CD8+ cytotoxic T lymphocytes and CD4+ helper T lymphocytes are essential for inducing tumor cell apoptosis via immune-mediated antitumor mechanisms." (PMID 40365348, 2025). "We found that Tbet+ICOS+ Th1-like CD4+ T cells expressed the highest level of PD-1 among tumor-infiltrating CD4+ Tconv, indicative of high tumor reactivity, and that in vivo treatment with 9D9 increased the proportion of PD-1+ CD4+ T cells producing IFNγ upon re-stimulation ex vivo." (PMID 40460830, 2025). "The prognostic value of infiltrating Tregs and CD4+ TILs might also be dependent on the volume of the primary tumor as some studies in more advanced CC showed improved survival with higher CD4+ and Tregs content." (PMID 41007768, 2025). "The proportion of tumor-infiltrating cytotoxic T cells (CD8+CD4−) in the MMSN@Dox treatment group significantly increased compared to that in the saline and other treatment groups, demonstrating a 2.74-fold and 1.46-fold elevation relative to the saline and Dox groups, respectively." (PMID 40871055, 2025). "Importantly, intratumoral injection of rAd.sT increased CD8+ T lymphocytes and CD4+ T memory cells in the peripheral blood, pointing to a direct anti-tumor immunological effect by suppressing TGF-β signaling." (PMID 41445946, 2025). "Effector T cells, primarily CD8+ cytotoxic T lymphocytes (CTLs) and CD4+ helper T cells, are critical for directly targeting and eliminating tumor cells through the release of cytokines such as IFN-γ, TNF-α, and IL-2, and the use of cytotoxic granules containing perforin and granzymes." (PMID 40475782, 2025). "Moreover, El1405 intervention significantly increased the levels of TNF-α, INF-γ, and CD8 in the tumor microenvironment, while decreasing the levels of CD4, IL-6, IL-10, and TGF-β." (PMID 40568973, 2025). "CD4 cell count was connected with decreased immune function and advanced tumor burden." (PMID 40969752, 2025). "Furthermore, the anti-tumor activity of CBD on the tumor microenvironment was evaluated after the depletion of CD4+T cells and CD8+T cells in murine models." (PMID 40475776, 2025). "In addition, lower baseline CD4+ and CD8+ T cell counts have been associated with worse tumor response and survival." (PMID 41281444, 2025). "Moreover, studies suggest that as tumor grade progresses, the proportions of both CD8+ and CD4+ tumor-infiltrating T cells tend to increase." (PMID 41300698, 2025). "Whether CD4+ T cells engineered with CD8-restricted TCR can hijack tumor cells to form such a triad to restore and improve CD8+ T cell functions will require further experimental investigations." (PMID 39893177, 2025). "Interestingly, we observed a significant increase in tumor volume in CD4-depleted mice treated with CBD as compared to CBD-treated wild-type mice suggesting the importance of CD4+T cells in CBD-mediated anti-tumor activity." (PMID 40475776, 2025).